FAAH (fatty acid amide hydrolase)
Diseases named in the same sentence as FAAH in open-access papers (continued):
Sharing a sentence is not in itself a finding about the gene and the disease.
endothelial dysfunction (1 paper, 2015). In vascular diseases, endothelial dysfunction is a systemic pathological state of the endothelium (the inner lining of blood vessels) and can be broadly defined as an imbalance between vasodilating and vasoconstricting substances produced by (or acting on) the endothelium. "Two other potential metabolites were also identified in this study: S-methyl-L-thiocitrulline is a potent NOS inhibitor to reduce nitric oxide production and endothelial dysfunction while O-arachidonoyl glycidol was reported to be an inhibitor of fatty acid amide hydrolase." (PMID 25889340, 2015).
endotoxemia (1 paper, 2022). "Increased concentration of AEA following LPS exposure in BAEC and reduced expression of the AEA degradation enzyme FAAH may therefore be sufficient to increase cytochrome-c release with addition of only 0.5 μM AEA in this model of endotoxemia associated inflammation." (PMID 36009180, 2022).
esophageal cancer (1 paper, 2020). A primary or metastatic malignant neoplasm involving the esophagus. "Co-expression analysis showed that PROM1 was significantly co-expressed with ProSAPiP1, FAAH, and LTA in esophageal cancer." (PMID 31164716, 2020).
fibrosis (1 paper, 2023). the formation of excess fibrous connective tissue in an organ or tissue in a reparative or reactive process. "URB878 was given daily for a total of 14 days in order to assess the possibility of FAAH inhibition for the treatment of fibrosis." (PMID 37373275, 2023).
focal epilepsy (1 paper, 2025). A seizure caused by a localized disorder. "In the Iranian population, FAAH rs324420 genotype and allele distribution were shown to be associated with generalized epilepsy and not with focal epilepsy." (PMID 39920787, 2025).
generalized epilepsy (1 paper, 2025). Epilepsy that is characterized by generalized seizure types and may have typical interictal and/or ictal EEG findings that accompany generalized seizure types (for example generalized spike-wave). "FAAH C384A genotype is associated with the risk of generalized epilepsy in Iranians." (PMID 39920787, 2025).
GI dysmotility (1 paper, 2022). "Cannabinoid 1 receptor antagonist, AM251 blocked the effects of URB597, which may demonstrate that FAAH inhibitor is a potential remedial strategy for GI dysmotility." (PMID 35878381, 2022).
hepatocellular carcinoma (1 paper, 2021). A malignant tumor that arises from hepatocytes. "For example, the involvement of the endocannabinoid system in the immune response of tumours was recently highlighted by the finding that the FAAH inhibitor URB597 may enhance the immune surveillance of human hepatocellular carcinoma cells." (PMID 34830856, 2021).
Hydrocephalus (1 paper, 2012). Hydrocephalus is an active distension of the ventricular system of the brain resulting from inadequate passage of CSF from its point of production within the cerebral ventricles to its point of absorption into the systemic circulation. "An additional sample with two events was a fetus with hydrocephalus found to have two duplication CNVs, on chromosome bands 1p33 (including the genes FAAH, DMBX1 and KNCN) and 10q11.22 (containing the genes SYT15, GPRIN2 and PPYR1), but parental samples were not available in this case." (PMID 23056206, 2012).
Hyperinsulinemia (1 paper, 2012). An increased concentration of insulin in the blood. "However, hyperinsulinemia in FAAH−/− mice was evident indicated by their AUC for plasma insulin which was 3 times higher compared to wild-type mice." (PMID 22442717, 2012).
hyperlipidemia (1 paper, 2024). "Biological backgrounds including gender, BMI, and FAAH rs324420 need to be taken into account when diets are used to prevent or treat low HDL‐C of hyperlipidemia, MetS, and cardiovascular disease in adolescents." (PMID 39619958, 2024).
knee osteoarthritis (1 paper, 2020). "However, a study performed on 74 patients with knee osteoarthritis found a lack of analgesic effect of a potent and selective FAAH1 inhibitor PF-04457845, despite decreasing activity of FAAH by >96% and increasing levels of the four endogenous substrates (fatty acid amides)." (PMID 32967120, 2020).
leukaemia (1 paper, 2016). "Another discovered therapeutic target with respect to fatty acid amides in leukaemia is fatty acid amide hydrolase (FAAH)." (PMID 26988915, 2016).
leukocytosis (1 paper, 2014). "Both low CNR1 and high FAAH levels correlated with lymphocytosis (p=0.016 and p=0.022, respectively) and with leukocytosis (p=0.0018 and p=0.047)." (PMID 25594062, 2014).
liver fibrosis (1 paper, 2015). "The involvement of CB1 and CB2 in modulating liver fibrosis, steatosis and cell regeneration has been repeatedly demonstrated; however, the particular role of AEA and 2-AG, as well as EC degrading enzymes FAAH and MAGL in the development of CHC is not well known." (PMID 25826533, 2015).
lung adenocarcinoma (1 paper, 2014). A carcinoma that arises from the lung and is characterized by the presence of malignant glandular epithelial cells. "Eleven of fifty seven (19.3%) lung adenocarcinomas showed high cytoplasmic expression of FAAH." (PMID 24811863, 2014). "We have shown that FAAH and CB1 receptor which is activated by AEA are expressed in lung adenocarcinoma patient samples and NSCLC cell lines A549 and H460." (PMID 24811863, 2014).
lysosomal storage disease (1 paper, 2021). A metabolic disorder caused by mutations in proteins critical for lysosomal function, including lysosomal enzymes, lysosomal integral membrane proteins, and proteins involved in the post-translational modification and trafficking of lysosomal proteins. "Only recently, it has been shown, for example, that oral treatment of sphingomyelinase-deficient mice (model of the lysosomal storage disease Niemann–Pick type A/B) with FAAH inhibitors alleviated neuroinflammation, retarded neurodegeneration, improved behavioral alterations, and extended life span." (PMID 34375644, 2021).
major depressive episode (1 paper, 2025). "Presently, a key gap in the literature is an absence of investigations of brain FAAH in major depressive episodes (MDE) of MDD." (PMID 40550956, 2025).
mental disorder (1 paper, 2024). A disease that has its basis in the disruption of mental process. "Taken together, the concurrent reduction of both CB1R and FAAH suggests a complex dysregulation of the endocannabinoid system, which may impair synaptic plasticity and contribute to maladaptive stress responses and the development of mental disorders." (PMID 39503008, 2024).
metastatic disease (1 paper, 2023). "Together, our findings highlight the potential of FAAH as a biomarker with prognostic value in luminal BC and as a therapeutic target in metastatic disease." (PMID 37253733, 2023).
methamphetamine dependence (1 paper, 2025). A drug dependence that is a psychological dependency on the regular use of methamphetamine. "FAAH rs324420 is widely researched in several diseases or physiological processes, such as motor performance, memory fading, and susceptibility to methamphetamine dependence." (PMID 39920787, 2025).
myocardial hypertrophy (1 paper, 2022). "Heart weight/tibia length (HW/TL) as a parameter of myocardial hypertrophy was significantly increased after 7d I/R in the FAAH−/− group, indicating that FAAH deficiency elevates hypertrophy during I/R." (PMID 36293543, 2022).
myocardial infarction (1 paper, 2017). Gross necrosis of the myocardium, as a result of interruption of the blood supply to the area, as in coronary thrombosis. "Moreover, a case-control study found a role for allele A of the FAAH 385 variant as a risk factor for myocardial infarction." (PMID 28814985, 2017).
Nausea (1 paper, 2021). A sensation of unease in the stomach together with an urge to vomit. "Despite the fact that these two nausea conditions have different molecular basis, the divergence between the two FAAH inhibitors may be due to a difference of selectivity and potency on FAAH as suggested by the authors, PF-3845 being more potent and selective than URB597." (PMID 33498245, 2021).
non-small cell lung carcinoma (1 paper, 2014). A group of at least three distinct histological types of lung cancer, including non-small cell squamous cell carcinoma, adenocarcinoma, and large cell carcinoma. "In this study, we have analyzed the role of FAAH inhibition in non-small cell lung cancer (NSCLC)." (PMID 24811863, 2014).
obstructive lung disease (1 paper, 2022). "In addition, a potential impact of AEA/FAAH signaling on other types of obstructive lung disease such as COPD may be of therapeutic relevance." (PMID 36396957, 2022).
peroxisomal disorders (1 paper, 2023). "Since inhibition of FAAH was shown to be neuroprotective, the observed alterations may contribute to neurodegenerative process in peroxisomal disorders." (PMID 37138705, 2023).
ptosis (1 paper, 2016). The drooping of the upper eyelid. "In FAAH+/+ and FAAH-/- mice, oleamide induced hypomotility, hypothermia, and ptosis, all of which were enhanced in FAAH-/- mice, with negligible binding to the CB1 receptor in brain extracts from either genotype." (PMID 27570505, 2016).
rheumatic diseases (1 paper, 2018). "Decreases of Mapk14 and Prkcg mRNA levels following FAAH inhibition highlights hopes for new treatment strategies of neuropathic components in rheumatic diseases, as seen with intrathecal administration of p38α MAPK and PKCγ inhibitors in a chronic constriction injury model of neuropathic pain." (PMID 29364174, 2018).
skin cancer (1 paper, 2023). "Since few reports have evaluated the role of FAAH inhibitors in counteracting tumor progression in skin cancers, we extended the study to the squamous carcinoma cell line A431." (PMID 38139209, 2023). "The ability of URB597 to contrast the EMT process provides insight into effective approaches that may also include the use of FAAH inhibitors for the treatment of skin cancers." (PMID 38139209, 2023).
Ta (1 paper, 2025). "In Ta tumors, commonly expressed glycoproteins were primarily associated with metabolic and regulatory activities, including pyruvate carboxylase activity, fatty acid amide hydrolase activity, SUMO binding, and sequence-specific single-stranded DNA binding." (PMID 40430030, 2025).
tauopathy (1 paper, 2024). Neurodegenerative disorders involving deposition of abnormal tau protein isoforms (tau proteins) in neurons and glial cells in the brain. "To investigate the suitability of FAAH/AEA as a novel sleep-promoting therapeutic target in PS19 Tauopathy/AD mice models, we selectively targeted AEA via the acute and sustained administration of the FAAH inhibitor compound PF3845 and measured sleep phenotypes." (PMID 38543105, 2024). "By using pharmacology and genetic knockout strategies, we evaluated fatty acid amide hydrolase (FAAH) as a therapeutic target to improve sleep and halt disease progression in a transgenic Tau P301S (PS19) model of Tauopathy and AD." (PMID 38543105, 2024).
trigeminal neuralgia (1 paper, 2023). Trigeminal neuralgia is a nerve disorder that causes a stabbing or electric-shock-like pain in parts of the face. "Here, we investigated the effect of URB937, a blood–brain barrier impermeant FAAH inhibitor, on experimentally induced mechanical allodynia in an animal model of trigeminal neuralgia." (PMID 38004491, 2023). "Here, we tested for the first time the effect of a blood–brain barrier (BBB) impermeant FAAH inhibitor in an animal model specific for trigeminal neuralgia." (PMID 38004491, 2023). "Here, we tested for the first time the BBB impermeant FAAH inhibitor URB937 in the pre-clinical model of trigeminal neuralgia based on IoN-CCI." (PMID 38004491, 2023).
tubular adenocarcinoma (1 paper, 2023). An infiltrating adenocarcinoma in which the malignant cells form tubular structures. "Moreover, in analysing whether FAAH was tissue-specific, we noted that FAAH was enriched in GC tissues relative to other common solid tumours, especially tubular adenocarcinoma." (PMID 36702852, 2023).
varicocele (1 paper, 2018). A condition characterized by the dilated tortuous veins of the spermatic cord with a marked left-sided predominance. "Noteworthy, none of the other ECS elements investigated (i.e., NAPE-PLD, DAGLα, FAAH, MAGL, CB1, and CB2) was affected by varicocele induction." (PMID 30539009, 2018).
vascular dementia (1 paper, 2023). A degenerative vascular disorder affecting the brain. "Additional studies in models of vascular dementia or alcohol-induced hippocampal damage have confirmed that the activation of CB1 receptors is important for the benefits obtained after FAAH inhibition in these pathological conditions." (PMID 37149645, 2023).
cancer (51 papers, 2010 to 2025). A tumor composed of atypical neoplastic, often pleomorphic cells that invade other tissues. "Mechanistically, FAAH knockdown in cancer-associated fibroblasts (CAFs) attenuated co-cultured BLCA cell viability, potentially mediated by CCL15 secretion." (PMID 40630945, 2025). "This contrasts with the findings of other studies where elevated FAAH expression was linked to poor outcomes in various cancers." (PMID 39575189, 2024). "Since FAAH in cancer cells modulates the apoptotic potential of endocannabinoids by promoting endocannabinoid hydrolysis, it was hypothesized that high levels of FAAH may be implicated in cancer cell proliferation." (PMID 37921652, 2023). "In the current study, drinkers presented hypermethylation at cg12671744, which might associate with downregulation of FAAH given that anti-correlation between cg12671744 methylation and FAAH mRNA expression has been reported in cancer studies." (PMID 30498460, 2018). "Some FAAH inhibitors have shown synergistic effects with chemotherapeutic drugs, which has become a research hotspot in cancer treatment, especially since clinical trials have shown that FAAH inhibitors have good tolerability and minimal toxicity." (PMID 39335103, 2024). "FAAH expression is upregulated in multiple tumor tissues, and its inhibitors have demonstrated anti-invasive and anti-metastatic effects on various cancer cells." (PMID 39335103, 2024). "FAAH inhibitors confer anti-invasive and antimetastatic effects on various cancer cells and also have synergistic effects with chemotherapeutic drugs." (PMID 37024452, 2023). "Over the past decades, anticancer effects have been observed for various FAAH inhibitors in several cancer cell lines." (PMID 37024452, 2023). "Reducing the turnover of eCBs prolongs their beneficial anti-tumor effects; however, the levels of FAAH were found to be higher or more downregulated than in healthy tissues depending on the cancer type." (PMID 38139209, 2023). "The pharmacological inhibition of FAAH demonstrated beneficial effects in several cancer cell lines by enhancing the anti-proliferative, pro-apoptotic, and anti-migratory capabilities of eCBs." (PMID 38139209, 2023). "Overexpression of FAAH showed a strong cancer-promoting effect, characterised by accelerated proliferation and cycle progression, enhanced metastasis, and decreased apoptosis." (PMID 36702852, 2023). "Further research exploring the therapeutic potential and impact of FAAH expression on cancer cells is warranted." (PMID 37921652, 2023). "FAAH is an integral membrane enzyme that hydrolyzes endocannabinoids, rendering them inactive, and FAAH inhibition is predicted to increase cancer cell death." (PMID 37921652, 2023). "All these data point to FAAH as an inhibitor of critical cellular processes in cancer cell migration and invasion, and therefore, in metastasis." (PMID 37253733, 2023). "Histological analysis of early detected tumors (T1) revealed that MMTV-neu:FAAH+/+ mice developed low-grade adenocarcinomas, while FAAH−/− mice developed solid high-grade carcinomas." (PMID 37253733, 2023). "The level of endocannabinoids is also often upregulated in cancers, as well as the level of FAAH and MAGL." (PMID 36291926, 2022). "Fatty acid amide hydrolase (FAAH) hydrolyzes the endocannabinoid anandamide and other N-acylethanolamines, which have been reported with anti-cancer effects." (PMID 36059494, 2022). "Accordingly, in this work, median survival with low FAAH levels in cancer cells was 10 months, whereas patients with moderate to strong FAAH immunoreactivity showed a median survival of 19.1 months." (PMID 34830856, 2021). "The antiproliferative effects of PEA on cancer cells was achieved by elevation of AEA levels within the cells due to inhibition of FAAH." (PMID 34503163, 2021).